CD4 (CD4 molecule)
Diseases named in the same sentence as CD4 in open-access papers (continued):
Sharing a sentence is not in itself a finding about the gene and the disease.
tumor (continued). "We determined that cryo-thermal therapy induced Th1-dominant CD4+ T cell differentiation and the downregulation of Tregs in B16F10 model, contributing to tumor-specific and long-lasting immune protection." (PMID 34576115, 2021). "Their activation by APCs prompt CD4+ T cells to activate the highly cytotoxic CD8+ T cells and to migrate to the tumor site." (PMID 34944847, 2021). "We found that ATP1B3 was significantly correlated with tumor purity and B cell infiltration, CD8+ T infiltration, CD4+ T infiltration, Macrophage infiltration, Neutrophil infiltration, and Dendritic cell infiltration." (PMID 33868261, 2021). "In the T‐cell subpopulation, a higher number of CD4+ T cells than CD8+ cells were maintained in both the PDOTSs and tumor tissues." (PMID 34240815, 2021). "We performed immunohistochemical analyses on post-treatment brains of each experimental group and investigated infiltrations of tumor tissues by T cells and macrophages/microglia using CD3, CD4, CD8, CD11b, CD163, C204, and PD1 and PD-L1." (PMID 34063518, 2021). "To further elucidate the underlying mechanisms of treatment response and resistance, we investigated immunosuppression within the tumor microenvironment (TME) by assessing expression of PD-1, Tim-3 and CD39 on tumor-infiltrating CD4+ and CD8+ T cells." (PMID 33688020, 2021). "Among them, the ccOC seems to be the most immunogenic: it more frequently carries the DNA microsatellite instability (MSI), has higher CD8+ tumor-infiltrating lymphocites (TILs), CD8+/CD4+ ratio, and higher PD-L1 levels." (PMID 34503248, 2021). "Yang and Lattime found that IL-10-expressing UBC cell line MB4 suppressed the ability of dendritic cells (DCs) to stimulate CD4+ and CD8+ T cell anti-tumor responses." (PMID 34541363, 2021). "The higher Tregs levels in tumor tissues indicated a worse prognosis and the FOXP3+ Tregs/CD4+ T cell ratio was an independent prognostic factor for OS." (PMID 33545975, 2021). "Mechanistically, activation of P2RX7 leads to increased production of IL-18 in a NLRP3-dependent manner, which in turn activates NK and CD4+ T cells to produce IFN-γ and consequently increases tumor immunogenicity." (PMID 33510147, 2021). "Using high throughput immunohistochemistry on paired normal and tumor tissue, we found similar trends of increased CD8+ and decreased CD4+ T cells from tumor versus normal renal tissue derived from the ccRCC patient samples." (PMID 33504936, 2021). "By developing and validating a rapid method detecting the majority of the real-time tumor-specific reactive CD8+ and CD4+ TIL repertoire in vitro, we have addressed a major ongoing issue in cancer immune-monitoring." (PMID 34707600, 2021). "They reported a high percentage of TILs (98%) in tumor samples, mainly CD3+ lymphocytes; although CD8+ and CD4+ lymphocytes were also expressed." (PMID 33902630, 2021). "Total CD3+ T-cells, as well as cytotoxic CD8+, helper CD4+, and regulatory FOXP3+ T-cells were evaluated in the stromal and intra-epithelial compartments in tumor samples before and after NACT." (PMID 32852603, 2021). "In these mice received low-dose decitabine-pretreated CD4+ T cells, the expression levels of cytotoxic marker granzyme B and TNF-α were also upregulated in tumor infiltrated CD4+ T cells." (PMID 33791306, 2021). "The anti-tumor efficacy of OX40/CD134 has been attributed to IT Treg depletion or inactivation and CD4 and/or CD8 stimulation." (PMID 35008305, 2021). "High CD73 expression levels can be detected on the surface of CD45+ immune cells, especially CD4+ and CD8+ T-lymphocytes (fold change compared to tumour-resident macrophages (TRMs), DCs, and neutrophiles: 46, 26 and 567 and 15, 8.4 and 181, respectively)." (PMID 34753903, 2021). "This supports the idea that tumour-producing CXCL10 is able to recruit CXCR3+ infiltrating cells, including CD4 T cells, CD8 T cells, and NK cells." (PMID 34956172, 2021).
tumor (continued). "Their results indicated a significant increase in interferon (IFN)-γ-producing CD4 and CD8 T cells and tumor-infiltrating CD4 and CD8 T cells." (PMID 33924844, 2021). "Whereas tumour infiltrating CD8+ T cell PD-1 and tumour PD-L1 expression was increased with treatment, peripheral CD4+ and CD8+ T cells retained strong anti-tumour activity." (PMID 34359633, 2021). "It was discovered that a low baseline proportion of CD4+ Tregs and post-treatment MHC-II expression on the tumor cells at the treated sites were significantly related to better clinical responses at distal sites." (PMID 35008305, 2021). "In GBM patients, decreases in CD4+ and CD8+ T cell numbers within the tumour and in the circulation are common, and the T cell population is prone to exhaustion." (PMID 33964937, 2021). "IL2RB activation via endogenous IL2 or biased therapeutic stimulation results in the expansion of anti-tumor immune cells, in particular CD8+, CD4+ and NK cells." (PMID 33928242, 2021). "While tumor killing is ascribed to CD8+ T cell function, pre-clinical and clinical studies have identified intra-tumoral CD4+ T cells that possess cytotoxic programs and can directly kill cancer cells." (PMID 34910940, 2021). "In the peripheral blood of SS patients, CD4+CD7− T cells, which were considered to be tumor cells, expressed both OX40 and OX40L, while CD4+ T cells in the peripheral blood of healthy subjects expressed OX40, but OX40L was weakly expressed." (PMID 34830466, 2021). "CD4+ T cells can be divided in regulatory T cells (Treg) and T helper (TH) cells, among which TH1, TH2, TH17 and TFH with various effects on tumor immunity." (PMID 33859645, 2021). "We also noted that the CD4+ and CD8+ TILs that trafficked through the hB16/HAGE+/Luc+ tumour model exhibited a remarkable upregulation of PD-1 that was independent of the immunisations." (PMID 34262856, 2021). "There was a strong positive correlation between the infiltration of CD20+ B lymphocytes and other immune profiles (i.e., CD4+, CD8+, and FOXP3+ TILs, and CD68+ and CD163+ macrophages) both in stroma and tumor nests." (PMID 33494389, 2021). "The expression intensities of programmed death-ligand 1 (PD-L1), CD4, CD8, CD20, FoxP3, and CK in whole tumor tissues were evaluated." (PMID 34502561, 2021). "The study emphasizes clearly a role for activated effector memory CD4 and CD8 T cells for tumor immunity during conditions of blockade of PD-1 signaling." (PMID 34912335, 2021). "CCR5 expression by both CD4+ and CD8+ T cells was reported to be crucial in boosting anti-tumor responses by optimizing helper-dependent CD8+ T cell priming at immunological synapse." (PMID 34836966, 2021). "In breast cancer mouse models, both SGJP and PA inhibit the numbers of MDSCs to increase the proportion of CD4+ T cells, CD8+ T cells, and NK cells in peripheral blood of mice, further improving the survival rates of mice and blocking tumor growth." (PMID 33748122, 2021). "As identified by the expression of CD4, CD25, and the FoxP3 transcription factor, Treg are frequently found in the tumor microenvironment and in the circulation." (PMID 35008832, 2021). "First, we showed that, compared to control VV, IL-36γ-VV greatly enhanced tumor site adaptive immune responses by increasing the tumor infiltration of CD3+ T lymphocytes, including both CD4+ and CD8+ T cells." (PMID 33538860, 2021). "They find that the combination of DNA vaccination of ENO1 and gemcitabine shows a significant reduction of circulating CD4 and CD8 T cells, which supports the increasing infiltration of these cells in tumor lesions in the pancreatic cancer-prone KC mice." (PMID 34671213, 2021). "The highest infiltration fraction in the tumor tissues was by M0 macrophages, CD8 T cells, M2 macrophages, CD4 memory resting T cells, and M1 macrophages." (PMID 33955820, 2021).
tumor (continued). "Based on the Tumor Immune Estimation Resource (TIMER) database, the relationship between PECAM1 expression and B cell, CD8+ T cell, CD4+ T cell, macrophage, neutrophil, and dendritic cell infiltration was weak in LUAD (P<0.01)." (PMID 33461176, 2021). "CD8+ cells, the major population of CTLs, are responsible for killing tumor cells in an MHC class I-matched manner, while CD4+ cells mainly provide help to CD8+ cells." (PMID 34553029, 2021). "In crosstalk with other cell types and in the presence of TGFβ, metastasis is induced by CD4+ T‐cell derived IL4 and macrophage‐derived WNT7B/EGF as well as CSF1 from tumor cells." (PMID 34459003, 2021). "For example, the expression of CX3CL1 has been confirmed to result in the infiltration of NK cells, DCs, CD4+, and CD8+ T cells into the tumor, which leads to an increase in the antitumor immune response." (PMID 35140706, 2021). "Tumors were further stained with CD4, CD8, and F4/80 to assess immune cell infiltrates in the tumor." (PMID 34063642, 2021). "The frequency of endogenous NK1.1+NKG2D+, CD4+NKG2D+ T and myeloid cells in all tumor types was similar to that of controls." (PMID 34721405, 2021). "Similar to our above results, IHC analysis showed that this phenotype was accompanied by increased infiltration of CD4+ and CD8+ cells in the tumor." (PMID 33754054, 2021). "In a preclinical NSG mouse model, administration of CD19-CAR-T using CD4-targeted lentiviral vector (CD4-LV) displayed TH1/TH2 phenotype of the CAR-T, with a superior and faster tumor killing ability than CD8-LV CAR-T cells alone or in combination with CD4-LV." (PMID 34012451, 2021). "More recently, our findings suggest that IL-21-producing CD4+ T cells are required for the formation of effector CX3CR1+ CD8+ TILs, which enhances tumor control." (PMID 33809259, 2021). "Expressions of IL-2 and IL-2 receptor by CD8+ cytotoxic T lymphocytes (CTLs) and tumor-infiltrating lymphocytes (TILs) were also reduced under the influence of PGE2, while PGE2 induced CD4+ Th2 cell activation." (PMID 34497832, 2021). "We subcutaneously inoculated syngeneic tumors in the Cd4-Cre+Lsd1f/f and littermate control mice and found that LSD1 depletion in T cells affected tumor growth variably across tumor models." (PMID 34819502, 2021). "Pre-clinical study on HNSCC mouse models have shown that SCH58261,a A2AR antagonist, significantly decreases the population of CD4+ FOXP3+ Tregs and promotes a CD8+ T cell-mediated antitumor response, which lead to a delay in tumor growth." (PMID 33422072, 2021). "It is found that NCT treatment did not alter the distribution of CD4+ T cells, CD8+ TRM cells (CD8+ CD103+), CD4+ TRM cells (CD4+ CD103+) and CD4+ GzmB+ T cells were significantly increased in the overall tumor area after neoadjuvant chemotherapy." (PMID 34631551, 2021). "The FLOW results showed that the percentage of CTLA-4+PD-1+ on CD4+ cells (Upper) and FoxoP3+CD25+ on CD4+ immunosuppressive Tregs (Lower) were lower in tumor allografts from combined treatment compared to other single treatments." (PMID 34093869, 2021). "Immunophenotyping of these thymic samples revealed a gradual switch from CD4+CD8+ DP thymocytes to immature single positive thymocytes and DN subsets, correlating with tumor progression." (PMID 33310759, 2021). "The analysis of tumor‐infiltrating T cells showed increased numbers of CD4+ and CD8+ T cells in the tumor microenvironment." (PMID 34026437, 2021). "Conversely, CD4 + FOX3 + TH2 cells (T reg = regulatory T cells), M2 macrophages, and myeloid-derived suppressor cells (MDSCs) suppress anti-tumor immune counterparts and drive tumor growth." (PMID 34952631, 2021). "IL-35 can specifically increase the expression of these receptors on CD4 and CD8+ tumor-infiltrating lymphocytes (TILs) within the TME, thereby depleting local T cells." (PMID 34093586, 2021).
tumor (continued). "Tumor cells are characteristically intermingled with reactive CD3+, CD4+, CD8+ T, and CD20+ B cells, macrophages, activated microglia, and astrocytes." (PMID 34944954, 2021). "A total of 32 samples were selected for CD20, CD68, CD4, Foxp3, CD8, and P16 (for tumor cell staining) expression analysis by multiple immunofluorescence (mIF) staining and CD3 expression analysis by IHC staining." (PMID 35145511, 2021). "DC-CX3CL1 cells injected intratumorally decreased the tumor growth due to an increase of intratumoral infiltration of CD4+ and CD8+ T cells with the induction of tumor-specific CTL, and improved overall mice survival." (PMID 33391453, 2021). "Most immune cells infiltrating tumours are Tumour Infiltrating Lymphocytes (TILs) consisting of CD3+ Tcells (CD8+ Tcytotoxic and CD4+ Thelper cells) as well as FOXP3+ Treg cells." (PMID 33810350, 2021). "Immunohistochemistry showed RNF135 expression and six immune cell types (B cell, CD8+ T cell, CD4+ T cell, macrophage, neutrophil, and dendritic cell) were high in normal HCC tissues and the expression were low in tumor tissues." (PMID 35145901, 2021). "The expression of CD3+ PD-1+TIM-3+ (median 5.91 (range 0.01–10.39) vs. 0.27 (range 0–0.63), p < 0.05), and CD3+CD4+ PD-1+TIM-3+ (median 3.41 (range 0–10.3) vs. 0.33 (range 0–1.6), p < 0.05), was significantly higher in the tumour than in the lymph node." (PMID 34439160, 2021). "In SB28-OVA intracerebral tumors harvested on day 12, we detected OVA-specific CD4 and CD8 T cells, including Ki-67+ cells, suggesting proliferation and trafficking to the tumor." (PMID 34083417, 2021). "In vivo, decitabine pre-treated CD4+ and CD8+ CAR T cells targeting the CD19 antigen resulted in complete tumor regression in mice and persisted longer than untreated CAR T cells." (PMID 34262562, 2021). "The decrease in the PB CD4 T cell compartment secreting IFN-γ, a Th1 cytokine involved in tumor immunity, observed in our cohort of patients seems to reflect severe inhibition of anti-tumor effector functions of these cells in MM." (PMID 34502204, 2021). "Additionaly, the frequency of tumor CD8+ and CD4+ cells that produce IFN-γ ex vivo in response to MCA205 cells in an ELISPOT assay was significantly increased after exposure to the combination therapy." (PMID 33637599, 2021). "In in vivo experiments, the infiltration abundance of helper CD4+ and cytotoxic CD8+ T cells was significantly increased in mice tumor tissues treated with nanoparticles." (PMID 34656118, 2021). "Enhancement of antitumor activity requires tumor neoantigen-specific CD8+ T cells to inhibit tumors via major histocompatibility complex- (MHC-) I and enhanced immunotherapy by activating CD4+ T cells via MHC-II." (PMID 34708131, 2021). "In this NET-rich TME, the majority of CD4+ and CD8+ tumor infiltrating lymphocytes expressed multiple inhibitory receptors, in addition these cells showed a functional and metabolic exhausted phenotype." (PMID 34899751, 2021). "CD4+ T cell IFN-γ-inducible chemokines CXCL9, CXCL10, and CXCL11 recruit effector T cells to the TME, direct tumor infiltration, and are key players in T cell homing." (PMID 34012451, 2021). "We performed a thorough immunohistochemical analysis on post-tumor tissues from simultaneous versus sequential treatments involving CD3, CD4, CD8, CD11b, CD163, CD204, and PD1, PD-L1." (PMID 34063518, 2021). "Tcm marker expression was significantly upregulated in the tumour-infiltrating dCAR T cells, including CD8-positive and CD4-positive dCAR T cells, on the 7th and 14th days after cell infusion." (PMID 33462245, 2021). "Despite concerns that organoid media would be unsuitable for immune cell viability, our study shows that relevant tumor‐infiltrating CD3+, CD4+, and CD8+ cells can be successfully retained in organoid media." (PMID 34240815, 2021). "First, we analyzed CD4+ and CD8+ T cell populations in the lymph nodes, spleens, and tumors of tumor bearing and non-tumor bearing WT and Pik3cg−/− mice." (PMID 33668795, 2021).
tumor (continued). "Sunitinib also reduces MDSC numbers which is correlated with Treg decrease in the tumor microenvironment and favors CD4+ and CD8+ infiltration in the tumor site while reducing PD-1 expression on CD8+ T-cells." (PMID 33854498, 2021). "A priori paradoxical, the number of circulating CD4+ TFH cells, which likely reflects the type of TFH cells infiltrating tumours, appears to be significantly increased in DLBCL cases, especially in more advanced stages of the disease." (PMID 34572910, 2021). "After tumor cells reach the bone microenvironment, they promote the growth of CD56+CD8+ T cells and memory CD4+ T cells in the bone microenvironment." (PMID 33869189, 2021). "All of these events promote the presentation of antigens to CD4+ T cells in the lymph nodes, which drive the maturation of B and CD8+ T cells that carry out an adaptive immune response against tumor cells." (PMID 33535555, 2021). "The TME is characterized by the complex interaction between malignant tumor cells, immune cells (e.g., CD8+ or CD4+ T cells), as well as stromal cells." (PMID 33791196, 2021). "Investigating the upstream signalling cues that trigger and maintain a pro-inflammatory CD4+ T cell phenotype could lead to the identification of therapeutic regimens that favour the generation and/or maintenance of self-antigen-biased, anti-tumour CD4+ T cell immunity." (PMID 32457487, 2021). "Further results demonstrate that the cytotoxicity of CD8+ Tregs in tumor cell killing is the basis of GVL effects and that the combination of CD4+ Tregs and CD8+ Tregs is an ideal therapy that would more effectively prevent GVHD and preserve GVL effects." (PMID 34899714, 2021). "Neoantigens accumulating on the surface of cancer cells can elicit the antitumor responses through the activation of CD8+ and CD4+ T cells in the TME, subsequently eliminating the tumor cells and thereby preventing cancer development and progression." (PMID 34777634, 2021). "In a separate patient cohort (n = 11), T cells were classified using CD3, CD4, CD8, FoxP3, and granzyme B in paired PBMC and single cell suspensions of tumor samples." (PMID 34926643, 2021). "Aberrant tumor angiogenesis contributes to immunosuppression and tumorigenesis through subvert effector CD8+ T cells and promotes regular CD4+ T cells infiltration." (PMID 34722280, 2021). "Effective elimination of tumor cells in vivo is mediated by CD8+ cytotoxic T cells (CTL) via interactions with HLA class I complexes, with help of CD4+ T helper cells (TH) via interactions with HLA class II complexes." (PMID 33592498, 2021). "In DLBCL patients, an increased level of TIM-3 was observed in both CD4+ and CD8+ T-cells, which was positively correlated with tumour stages." (PMID 33430146, 2021). "TILs refer to lymphocytes that leave the blood and enter the tumor, which are a major component of the TME, including CD8 + T cells, CD4 + T cells, B lymphocytes and natural killer (NK) cells." (PMID 35047411, 2021). "ICB activates CD4+ and CD8+ T cells in the TME, remodels the tumor vasculature, and indirectly enhances their antitumor activity." (PMID 34294146, 2021). "Overexpression of cyclin G2 reduced the tumor-infiltrating Tregs and dramatically shifted the balance in favor of IFN-γ + CD4 + and IFN-γ + CD8 + T cells over Tregs in tumors." (PMID 34452627, 2021). "The distribution of lymphocytes within the tumor evaluated through tissue microarrays revealed that high density of T lymphocytes (CD4+ and CD8+) in the tumor stroma correlated with better prognosis." (PMID 35069581, 2021). "The CD45+CD4+ depletion and CAR expression in the CD3+CD8+ population agreed with the tumor burden analyzed by IVIS signal and tumor size in each mouse." (PMID 34162832, 2021). "CD8+ T cells are the main effector cells, while CD4+ T cells can induce and activate CD8+ T cells in the tumor microenvironment." (PMID 33764442, 2021).